Y_RNA (Y RNA )
Gene: Miscellaneous RNA gene on chromosome 6 (75,928,513 to 75,928,625, forward strand). Ensembl gene ENSG00000200040.
Homologues: Orthologues: chimpanzee Y_RNA (100% identical), macaque Y_RNA (95% identical), zebrafish Y_RNA (59% identical). Paralogues in human: Y_RNA (80% identical), RNY1 (79% identical), Y_RNA (79% identical), Y_RNA (78% identical), RNY1P7 (77% identical), Y_RNA (77% identical), RNY1P11 (76% identical), Y_RNA (76% identical), RNY1P8 (75% identical), Y_RNA (75% identical), RNY1P5 (74% identical), Y_RNA (74% identical), and 91 more.